SMC4 (structural maintenance of chromosomes 4)
Diseases named in the same sentence as SMC4 in open-access papers (continued):
Sharing a sentence is not in itself a finding about the gene and the disease.
cancer (continued). "In vivo tail-vein metastasis models confirm that SMC4 enhances distant dissemination, aligning with its role in TGF-β pathway activation in other cancers." (PMID 40933894, 2025). "Using publicly available patient derived datasets obtained from TCGA, we determined that all eight condensin genes (SMC2, SMC4, NCAPD2, NCAPD3, NCAPG, NCAPG2, NCAPH, and NCAPH2) are frequently altered in at least 12 common cancer types." (PMID 31357676, 2019). "And it has been reported that overexpression of SMC4 activates JAK2/Stat3 and TGFβ/Smad pathway and promotes aggressiveness of cancer cells." (PMID 31871499, 2019). "The condensin complex has been suggested as a potential therapeutic target for cancer, and human homologs YCG1/NCAPG2, YCS4/NCAPD2, and SMC4/SMC4 are synthetic lethal with the Ras oncogene." (PMID 31660150, 2019). "Four proteins identified in the faecal proteome are potential biomarkers of the cancer, including diacylglycerol kinase (DGKB, DGK), mastermind-like transcriptional coactivator 2 (MAML2), structural maintenance of chromosomes 4 (SMC4), IG domain-containing protein and transglutaminase 2 (Tgm2)." (PMID 35202347, 2022). "Moreover, genes that are upregulated and downregulated at both RNA and protein levels across multiple types of cancers were identified and defined as PCUGs and PCDGs, respectively, which encompass a large number of oncogenes such as MKI67, TRIP13, SMC4, UBE2C, CDK1, and TOP2A." (PMID 39884577, 2025). "However, up to now SMC4 and PBC have never been connected, as well as an association of PBC and cancer only exists in clinical ratios." (PMID 22606281, 2012). "As reported by others, highly expressed SMC4 may upregulate the expression of PLK1, leading to cancer progression and poor prognosis in non-TNBC." (PMID 33460400, 2020).
Breast (2 papers, 2016 to 2019). "In conclusion, we reveal that SMC4, which is essentially involved in lung development, is closely associated with lung ADC progression and prognosis." (PMID 27687868, 2016). "Furthermore, we found that SMC4 is upregulated in lung ADC tissues compared with matched adjacent normal tissues and acts as an independent predictor of poor prognosis." (PMID 27687868, 2016).
adenocarcinoma (1 paper, 2024). A common cancer characterized by the presence of malignant glandular cells. "The present results also exhibit that among the amplified genes, the following eight genes involved in the cell cycle were found to be amplified in more than 5% of HGSO adenocarcinoma patients: ATAD2, ASF1B, CCNE1, CDC20, CDCA8, RECQL4, RNASEH2A, and SMC4." (PMID 39199556, 2024).
SMC4 also shares sentences with these, for which no sentence is quoted: pyothorax (2 papers); acute lymphoblastic leukemia (1); anaplastic astrocytoma (1); astrocytoma (1); bacterial infection (1); bladder cancer (1); breast adenocarcinoma (1); chronic lymphocytic leukemia (1); chronic myeloid leukemia (1); colon (1); diabetes (1); head and neck cancer (1); head and neck tumor (1); kidney cancer (1); liposarcoma (1); lymph node metastasis (1); malignant fibrous histiocytoma (1); myeloma (1); myxofibrosarcoma (1); myxoid/round cell liposarcoma (1); non-small cell lung carcinoma (1); oligoastrocytoma (1); oligodendroglioma (1); ovarian carcinoma (1); pleomorphic liposarcoma (1); Primary Biliary Cirrhosis (1); prostate tumors (1); rectal cancer (1); Renal Cell Cancer (1).